CCDC144CP (coiled-coil domain containing 144C, pseudogene)
Synonyms: CCDC144C
Gene: Transcribed unprocessed pseudogene on chromosome 17 (20,321,317 to 20,402,192, forward strand). Ensembl gene ENSG00000154898.
Diseases named in the same sentence as CCDC144CP in open-access papers:
CCDC144CP is named in the same sentence as 1 disease in open-access papers, as found by Europe PMC text mining. Sharing a sentence is not in itself a finding about the gene and the disease.
CCDC144CP shares sentences with these, for which no sentence is quoted: lung adenocarcinoma (1 paper).